CCL2 (C-C motif chemokine ligand 2)
Diseases named in the same sentence as CCL2 in open-access papers (continued):
Sharing a sentence is not in itself a finding about the gene and the disease.
cutaneous leishmaniasis (12 papers, 2012 to 2023). Leishmaniasis affecting the skin. "and cutaneous leishmaniasis involves the production of multiple Th1-associated chemokines including CCL2, CCL7, CXCL9, and CXCL10." (PMID 34543348, 2021). "Ritter and Korber demonstrated the key role of MIG in the self-healing of localized cutaneous leishmaniasis, confirming that lesions exhibited a strong expression of Th1-associated chemokines, such as CCL2/MCP-1, CXCL9/MIG, and CXCL10/IP-10." (PMID 37242376, 2023). "In experimental cutaneous leishmaniasis, the upregulation of miR-294 regulated Ccl2/Mcp-1 mRNA levels and infectivity in L. amazonensis infected BALB/c bone marrow-derived macrophages." (PMID 34178725, 2021). "It has been reported that tissue lesions of human cutaneous leishmaniasis due to L. tropica express high levels of intralesional iNOS and CCL2, indicating that NO likely promotes parasite killing by macrophages via CCL-2-mediated stimulation." (PMID 24098824, 2013). "In cutaneous leishmaniasis, a number of chemokines were shown to be expressed in Humans, of which CCL2, CCL19 and CCL17." (PMID 22457760, 2012). "CCL2 has been shown to play an important role in early immunity against cutaneous leishmaniasis." (PMID 34281214, 2021).
E. coli infection (12 papers, 2016 to 2026). "Instead, E. coli infection triggered a robust response in the endothelial cells, as evident by elevated levels of IL-6, CCL2, and CX3CL1." (PMID 41408425, 2026). "We found that E. coli infection of the mouse prostate increased Lyz2+ cell abundance and expression of Ccl2 mRNA." (PMID 39748675, 2025). "E. coli infection triggered a massive increase in transcript levels for Ccl2, iNos or Il6, a modest increase in Il10 transcripts but totally abrogated IL4 transcript expression in both Sham- and CLP-operated mice." (PMID 32425929, 2020).
medulloblastoma (12 papers, 2011 to 2025). A malignant, invasive embryonal neoplasm arising from the cerebellum. "IDO1 expression in medulloblastoma cells causing Treg expansion by CCL2 mediator." (PMID 34095111, 2021). "Using ELISA, we confirmed elevated levels of CCL2 in medulloblastoma tissue compared to normal cerebellum." (PMID 31160587, 2019). "Mining published microarray data, we found a significant increase of CCL2 expression in human SHH medulloblastomas, which further supports our murine model." (PMID 31160587, 2019). "It was recently demonstrated that a hematogenous route for medulloblastoma leptomeningeal metastases is active, and the C-C Motif Chemokine Ligand 2 (CCL2) production by tumor cells play a pivotal role in such an occurrence." (PMID 29584702, 2018). "To define the role of inflammatory monocytes in medulloblastoma, we investigated whether deletion of Ccl2 from TME will affects macrophage infiltration, but we found that their numbers were unchanged." (PMID 31160587, 2019). "The results also suggest that IL-17 in mice might activate splenocytes and/or medulloblastoma cells to produce chemokines Ccl20 and Ccl2, which might promote splenocyte recruitment and anti-tumor activity." (PMID 26684834, 2015). "We speculated that IL-17 might promote IFN-gamma, IL-6, IL-23, CCL-20, and Ccl2 expressions in the subcutaneous medulloblastoma model." (PMID 26684834, 2015). "Furthermore, our study showed that injecting IL-17 significantly increased the IFN-gamma, IL-6, IL-23, Ccl2, and Ccl20 chemokine productions in medulloblastoma xenografts in vivo." (PMID 26684834, 2015). "These may be due to the significant increase of monocyte chemotactic protein-1 (MCP-1/CCL2), which could recruit TAMs and promoting M2 macrophage polarization, in human SHH medulloblastoma." (PMID 35860588, 2022). "Furthermore, overexpression of the chemokine CCL2 was sufficient to drive LM in infrequently metastatic medulloblastoma lines ONS76 and MB002, while short hairpin RNA–mediated knockdown of CCL2 in the highly metastatic D425S medulloblastoma line decreased metastasis." (PMID 38451255, 2024).
myositis (12 papers, 2012 to 2026). "When we analyzed the cytokines behavior according to the myositis core set measures, we observed an association with CCL2 and IL-1β, showing higher serum levels when the MYOACT score is equal to zero, which might be interpreted as clinical remission." (PMID 39456842, 2024). "It has been shown distinct evidence of CCL2 implication in myositis including its expression at mRNA level in patient muscle tissue, CCL2 protein expression in endothelial cells, as well as higher levels of CCL2 in muscle tissue of IIM patients." (PMID 36271295, 2022). "In particular, chemokines, a class of small cytokines with potent chemotactic activity, such as IL-8 (CXCL8), Mig (CXCL9), IP-10 (CXCL10), RANTES (CCL5), and MCP-1 (CCL2), are overexpressed during myositis in infiltrating inflammatory cells, extracellular matrix, and muscle fibers." (PMID 24895631, 2014). "Significant variation of cytokine levels in sera such as IL-1RA or CCL-2 was observed but did not allow segregating sIBM patients from others myositis controls because of overlap between groups." (PMID 24594700, 2014). "In order to move towards the role of myokines in the modulation of myositis pathology, we mention an in vitro study that demonstrated that overexpression of MHC I in C2C12 cell line myotubes led to the release of inflammatory chemokines CCL2 and CCL5 via the ER stress pathway." (PMID 32775472, 2020).
respiratory failure (12 papers, 2005 to 2024). The significant impairment of gas exchange within the lungs resulting in hypoxia, hypercarbia, or both, to the extent that organ tissue perfusion is severely compromised. "Besides expression of pro-inflammatory cytokines, such as IL-1β and TNF-α, the expression of chemokines CCL2, CCL3, CCL20, CXCL1, CXCL3, CXCL10, IL-8 was shown likely to contribute to clinical observation of excessive inflammatory tissue damage, lung injury, and respiratory failure." (PMID 33362782, 2020).
status epilepticus (12 papers, 2009 to 2024). Status epilepticus is defined as a continuous seizure lasting more than 30 min, or two or more seizures without full recovery of consciousness between any of them. "In animal models, expression of CCL-2 increased after status epilepticus and in a model of systemic inflammation with seizures." (PMID 36499038, 2022). "In this work CCR2 and CCL2 expression were examined following status epilepticus (SE) induced by pilocarpine injection." (PMID 20034406, 2009). "During the inflammation, chemokines such as CCL2, CCL3, and CCL 5 can activate pathways leading to status epilepticus." (PMID 31632233, 2019). "MCP-1 (CCL2) was significantly increased in the contralateral and ipsilateral hemisphere of both Cav KO mice; these results are in agreement with previously published work that demonstrated increased expression in a pilocarpine model of status epilepticus." (PMID 24593993, 2014). "However, alterations to the expression patterns of CCL2 and CCR2 have not been examined following status epilepticus (SE) in a rat experimental model." (PMID 20034406, 2009).
chorioamnionitis (11 papers, 2012 to 2024). A morphologic finding indicating inflammation of the fetal sac membranes. "Ccl2 and Ccl3 code for known inflammatory chemokines that are elevated in chorioamnionitis-exposed preterm infants." (PMID 38481391, 2023). "Our results suggest that the brain injury in fetuses exposed to chorioamnionitis could be mediated by circulating IL-6 and/or CCL2." (PMID 27596440, 2016).
cryptococcal infection (11 papers, 2013 to 2025). "Following a cryptococcal infection, chemokines such as CCL2, CXCL1, CCL5, and CXCR3 ligands (CXCL9, 10, and 11) were secreted by astrocytes and T cells were recruited into the brain in a CXCR3-dependent manner." (PMID 36294634, 2022). "During cryptococcal infection, the lack of host 5-LO had the opposite effect on the production of proinflammatory cytokines like IL-6, G-CSF, and CCL2, suggesting that Cryptococcus can stimulate the production of these cytokines independently of the host LTB4." (PMID 39082787, 2024). "Although CCL4 is increased in the lungs of various animal models and in the human cerebrospinal fluid in response to C. neoformans infection, the role of this chemokine in cryptococcosis is still not well understood and appears not to be as critical as CCL2." (PMID 38033163, 2023).
cystitis (11 papers, 2013 to 2025). Inflammation of the urinary bladder. "The cystitis was associated with enhanced bladder mRNA expression levels of the inflammatory cytokines, Cxcl10, Ccl2, Il18, Tgfb, and Tnfa." (PMID 35647939, 2023). "We examined the inflammatory mediators, BDNF, NGF, VEGF, IL-6, and CCL2, and signaling kinases, pERK and pAKT, in the urinary bladder and LP, due to their established involvement in CYP-induced cystitis." (PMID 35528149, 2022). "Here, we examine inflammatory mediators (e.g., NGF, BDNF, VEGF, CCL2, IL-6) previously shown to increase expression and exhibit functional effects in micturition pathways in rodent models of CYP-induced cystitis." (PMID 35528149, 2022). "Prevention by oral gavage of imatinib reduced VEGFaa, VEGFab, BDNF, IL-6 and CCL2 mRNA, and VEGF and IL-6 protein expression in the LP and whole bladder, respectively, in mice with acute CYP-induced cystitis." (PMID 35528149, 2022). "CCL2/CCR2 interactions at the level of the urothelium and suburothelial nerve plexus in the urinary bladder are likely to contribute to bladder dysfunction and increased somatic sensitivity following CYP-induced cystitis." (PMID 24738044, 2014). "Imatinib prevention by oral gavage (250 mg/kg) significantly (p ≤ 0.05) decreased VEGFaa, VEGFab, IL-6, CCL2 and BDNF LP mRNA but did not affect NGF LP mRNA in mice with 4 h CYP-induced cystitis (1.6–6.5-fold)." (PMID 35528149, 2022). "Imatinib treatment via transurethral bladder infusion did not significantly affect CCL2, IL-6, BDNF, NGF, VEGFaa or VEGFab LP mRNA or urinary bladder protein expression in female mice with 4 h CYP cystitis." (PMID 35528149, 2022).
dry eye (11 papers, 2010 to 2025). "Expression of NF-kB associated or mediated inflammatory factors that have been found to increase or contribute to dry eye pathogenesis, including myd88, cytokines il12a, il12b (a subunit shared by IL-23 and IL-12), ltb and chemokine ccl2, was evaluated by PCR." (PMID 37036417, 2023). "Increased expression of NF-kB regulated cytokines (il12a, il12b, and ltb) and the chemokine ccl2 that are involved in dry eye pathogenesis was also observed." (PMID 37036417, 2023). "These cellular expressions explain the 3.23-fold increase of CCL2 mRNA observed in dry eye patients." (PMID 29673232, 2018). "Therefore, our aim was to analyze and characterize in vitro conjunctival CCL2 induction in a hyperosmolar model of dry eye and to determine the relationship between NFAT5 and CCL2 on HeLa-modified conjunctiva-derived cells." (PMID 27486749, 2016). "Indeed, animals with dry eye receiving CCR2 antagonist presented a decrease in corneal alterations and in pro-inflammatory cytokines TNF-α and IL-1β on the ocular surface, confirming the importance of CCL2 in the pathology." (PMID 27486749, 2016).
gingivitis (11 papers, 2013 to 2025). A disorder involving inflammation of the gums; may affect surrounding and supporting structures of the teeth. "A significant dose-dependent increase in the secretion ofcytokines IL-6, CXCL8, CCL2, and CCL5 was found for gingiva equivalents exposedto commensal, gingivitis, and cariogenic microbiome." (PMID 28892653, 2018).
head and neck cancer (11 papers, 2016 to 2025). A primary or metastatic malignant neoplasm affecting the head and neck. "In this study, we analyzed the immune regulatory properties of EGFR signaling in head and neck cancer cells and showed that it suppresses type 1 cytokine-induced expression of CCL2, CCL5, CXCL9, CXCL10 and IL-6 while promoting the expression of IL-1β." (PMID 30192802, 2018). "The production of monocyte chemotactic protein-1 (MCP-1, also known as CCL2) in the tumor microenvironment is recognized as having a crucial role in the growth, dissemination, and metastasis of head and neck cancer." (PMID 33330077, 2020). "Other significantly elevated cytokines detected in the saliva of head and neck cancer patients included CX3CL1, CCL2, CXCL1 and CCL15, most of which correlated with UWS secretion rates and objective oral dryness (CODS)." (PMID 32911805, 2020).
hepatitis C (11 papers, 2007 to 2025). "CCL2 may be a common regulator and novel therapeutic targets in hepatitis C and MASH." (PMID 39605886, 2024). "We selected two target proteins (CCL2 and STAT1) with the strongest regulatory interaction with NASH and hepatitis C for molecular docking analysis to predict their potential therapeutic effects." (PMID 39605886, 2024).
mesothelioma (11 papers, 2014 to 2025). A usually malignant and aggressive neoplasm of the mesothelium which is often associated with exposure to asbestos. "Mesothelioma cells, orchestrate the release of macrophage-attractant factors such as interleukin (IL)-8, IL-6, C-C motif chemokine ligand 2 (CCL2/MCP-1), G-CSF, GM-CSF, and MIP-1α, key players in sustaining tumor growth." (PMID 40016284, 2025). "Anti-CCL2 neutralizing antibodies reduce mesothelioma growth and tumor volume, switching the polarization of tumor infiltrating macrophages to a more anti-tumor phenotype." (PMID 34194430, 2021). "The dependence on mesothelioma stage was still apparent after removal of the two mesothelioma patients with exceptionally high levels of serum CCL2 from data analysis." (PMID 31823764, 2019). "We found that serum CCL2 levels were increased in mesothelioma patients and that this increase was dependent on advancing mesothelioma stage." (PMID 31823764, 2019). "After adjusting the data, the estimated mean CCL2 level in the serum of the mesothelioma patients is significantly elevated compared to the Possibly Exposed (no apparent disease) group, and this increase is dependent on the stage of the disease." (PMID 31823764, 2019). "Removal of these two patients reduces the serum CCL2 levels in the mesothelioma all patients, stage 3 patients, and stage 4 patients groups to 368.5 ± 138.1, 402.7 ± 123.2, and 420.5 ± 141.9, respectively." (PMID 31823764, 2019). "Two patients in the Mesothelioma group, patients 31 and 50, had extraordinarily high levels of serum CCL2." (PMID 31823764, 2019). "The increase in the serum levels of CCL2 in the mesothelioma patients was dependent on the stage of the disease." (PMID 31823764, 2019). "The mean CCL2 level in the serum of the mesothelioma patients was significantly elevated compared to both the healthy volunteers who have not been exposed to asbestos and the healthy subjects who have possibly been exposed to asbestos." (PMID 31823764, 2019). "The results of trials with patients with a similar pattern of CCL2 as mesothelioma patients will have important implications for the treatment of mesothelioma." (PMID 31823764, 2019). "Monocytes migrate toward malignant pleural fluid or mesothelioma cell line supernatant and neutralizing antibodies to CCL2 or CCR2 substantially reduce this migration in Transwell experiments." (PMID 31867277, 2019). "Reanalysis of the data adjusting for age and gender also indicated elevated levels of serum CCL2 depended on mesothelioma stage." (PMID 31823764, 2019). "The mean CCL2 level in the serum of the mesothelioma patients is significantly elevated compared to the Possibly Exposed (no apparent disease) group, and this increase is dependent on the stage of the disease." (PMID 31823764, 2019). "CCL2 levels are elevated in mesothelioma patients and the increase is dependent on the stage of the disease." (PMID 31823764, 2019). "After removal of these two patients’ data from analysis, serum CCL2 was still elevated in mesothelioma patients." (PMID 31823764, 2019). "The current study was undertaken to investigate serum CCL2 levels in mesothelioma patients." (PMID 31823764, 2019). "Another aspect of increased CCL2 in the serum of mesothelioma patients is that it may be possible to use serum CCL2 to monitor a patient’s response to treatment." (PMID 31823764, 2019). "Mesothelioma patients 31 and 50 had exceptionally high levels of CCL2." (PMID 31823764, 2019). "Since mesotheliomas are heavily infiltrated by macrophages and likely to be infiltrated by MDSCs, our finding that CCL2 is elevated in the serum of patients with advanced mesothelioma is consistent with a disease in which the CCL2/CCR2 axis and myeloid-derived cells play an important part." (PMID 31823764, 2019).
mesothelioma (continued). "Consequently, therapies that prove effective against other cancers in which the CCL2/CCR2 axis and myeloid-derived cells are associated with disease progression may also prove effective with mesothelioma patients." (PMID 31823764, 2019). "Mesothelioma cells attract monocytes in the TME though releasing some chemokines, such as chemokine (C-C motif) ligand 2 (CCL2), chemokine (C-C motif) ligand 4 (CCL4), chemokine (C-C motif) ligand 5, and C-X-C motif chemokine ligand 12 (CXCL12)." (PMID 38259475, 2023). "This is consistent with the premise that the CCL2/CCR2 axis and myeloid-derived cells play an important role in mesothelioma and disease progression." (PMID 31823764, 2019). "Chemokine signals that attract monocytes in mesothelioma include CCL2, CCL4, CCL5, and CXCL12 and these appear to be of mesothelioma cell origin." (PMID 31867277, 2019). "Interestingly, chemokines involved in monocyte/macrophage recruitment and mobilization such as CCL2, CCL3, CCL4, and CCL7 were downregulated in the mesothelioma cell line compared to two other tested cell lines." (PMID 39768223, 2024). "In this study we measured the levels of CCL2 in the serum of 41 healthy volunteers who have not been exposed to asbestos, 356 healthy subjects who have possibly been exposed to asbestos, and 50 mesothelioma patients." (PMID 31823764, 2019). "Re-analysis of the data after adjusting for age and gender did not change the conclusions of the study: serum CCL2 was elevated in mesothelioma patients." (PMID 31823764, 2019). "Moreover, ERK5 ablation in malignant mesothelioma cells is accompanied by a significant reduction in tumor size as a result of the downregulation of critical angiogenesis-related (IL-8, VEGF) and proinflammatory (RANTES/CCL5, MCP-1/CCL2) cytokines." (PMID 35053510, 2022). "Therefore, our data indicate that serum CCL2 levels were increased in mesothelioma patients and this increase was not dependent on the age of the patients in the Mesothelioma group or on the presence of the two patients in the Mesothelioma group with exceptionally high levels of serum CCL2." (PMID 31823764, 2019). "However, it is known that serum CCL2 levels increase with normal aging, and analysis of the age of the patients using the Kruskal-Wallis (one-way ANOVA) test showed an age difference between the patients in the Possibly Exposed (no apparent disease) and the mesothelioma groups." (PMID 31823764, 2019).